TERT (telomerase reverse transcriptase)
Diseases named in the same sentence as TERT in open-access papers (continued):
Sharing a sentence is not in itself a finding about the gene and the disease.
tumor (continued). "Although several studies reveal the impact of mitochondrial translocation of telomerase on drug resistance in HCC cell lines, the cellular distribution and telomere-independent activities of TERT has not been investigated in tumor tissues of HCC patients." (PMID 28460432, 2017). "The dynamic relationship between E6 and TIP60, the reduction in the tumor size upon overexpression of TIP60 as well as reports of TIP60 being present at the TERT promoter, have led us to question if TIP60 can regulate TERT expression and if this regulation is dependent on E6." (PMID 29045464, 2017). "We describe here the exploitation of the therapeutic efficacy of our anti-TERT-based ACT approach in more aggressive haematological cancer settings, such as AML and B-ALL, to validate its versatility as a widespread anti-tumour immunotherapy for leukemic diseases." (PMID 29152058, 2017). "Gene expression analysis using quantitative Reverse-Transcriptase Polymerase Chain Reaction (qRT-PCR) revealed that TERT messenger RNA (mRNA) expression was significantly higher in HCC tissues than it was in background, non-tumor liver tissue (at least 2 cm from the HCC) and normal liver tissues." (PMID 28947783, 2017). "In conclusion, TERT promoter mutations are very frequent in HCC with different etiologies and are tumor specific given their constant absence in non-tumor tissues." (PMID 28529542, 2017). "The analyses of TERT promoter and CTNNB1 mutations on HCC tumor samples have not been performed in the Korean population, where HBV-related HCC is prevalent." (PMID 27661004, 2016). "Several studies have, indeed, reported that TERT mRNA levels and telomerase activity are higher in poorly differentiated SCC, increase with tumor stage, and are associated with lymph node involvement or extracapsular extension of lymph node metastases." (PMID 27501725, 2016). "Moreover, multilineage differentiation, karyotype, colony formation in soft agar, and tumor formation in nude mice of SHED and TERT-SHED were also examined." (PMID 27044500, 2016). "Instead, TERT activity is restored in up to 90% of HCC, compared to the 21% of non-tumor tissue." (PMID 27276713, 2016). "Consistent with the levels of nuclear TERT protein identified, telomerase activity was low in the non-metastatic primary tumor." (PMID 25435972, 2015). "Thus, the combined mannan-modified TERT and VEGFR-2 adenovirus confers potent anti-tumour immunity by targeting both tumour cells and intratumoural angiogenesis." (PMID 26085010, 2015). "Conceivably, TERT down-regulation and telomere dysfunction mediated by 5-AZA may contribute to the anti-tumor activity of DNMTIs." (PMID 25682873, 2015). "Furthermore, 86 (0–12 per tumor) HBV integrations were identified with 2 and 5 recurrent integrations at the TERT and MLL4 loci, respectively, which is consistent with previous studies." (PMID 25526364, 2014). "In all four cases, the breakpoints did not disrupt the exons and TERT was expressed in tumor but not in the matched normal tissue (data not shown)." (PMID 25159915, 2014). "Further, the high prevalence of TERT promoter mutations not only in MLS round cell variants but also in MLS with a pure myxoid phenotype, and this irrespective of tumor grading, implies that these mutations act rather as driver than passenger mutations." (PMID 24726063, 2014). "Rats transplanted with untransfected or TERT transfected BMSCs did not die showed no tumour formation 24 weeks after transplantation." (PMID 24887495, 2014). "Also, to dissect out the benefit of anti-oxidant rich seaweed polyphenols in targeting tumor progression markers, first, we investigated the transcriptional regulation of Bcl2, EGFR, PDGFA, VEGF, AKT, TERT, kRas and FGF in PC cells." (PMID 23613993, 2013). "The higher expression of both TERT and TINF2 may also protect DFT cells from genomic instability and enhance tumour proliferation." (PMID 22952882, 2012).
tumor (continued). "TERT and TINF2 expression showed substantial variation across tumour samples." (PMID 22952882, 2012). "Analysis of a number of other genes that are strongly and specifically expressed in tumour over normal lung, including SERPINB5, TERT and PRAME, showed marked allelic expression imbalances in the tumour tissue in the context of balanced or only marginally imbalanced relative allelic copy numbers." (PMID 16222316, 2005). "In contrast, with TRT-L20, TEL-1, TERT and Ab-2 antibodies, no specific stained band was observed using several cell line lysates or from tumour samples." (PMID 15026805, 2004). "Although in more than half (57%) of the PTCs showing variations in TERT gene dosage was found an increase in TERT copy number in all the tumor samples analyzed in each case, not in all of the areas genotyped in those cases the increase reached the established amplification threshold." (PMID 40272676, 2025). "There is accumulating evidence that the telomerase enzymatic subunit TERT possesses further functions independent of telomere maintenance in the tumor and the microenvironment, including induction of EMT which is a hallmark of tumor progression." (PMID 39222177, 2025). "In non-MNA tumours, it has been shown that telomere maintenance is frequently achieved either through (i) genomic rearrangements that place TERT under the control of strong enhancer elements or (ii) ALT, which is associated with ATRX alterations in 55–60% of all ALT-positive cases." (PMID 40713849, 2025). "Moreover, the impact of TERT amplification alone or in combination with TPM on tumor relapse and patient survival has not been assessed in PTCs." (PMID 40272676, 2025). "Consistently, we observed that TERT overexpression induced a modification of mitochondrial gene expression: mRNA levels were significantly reduced in normal cells (HFFF2TERT-HA), while in tumor cells (U2OSTERT-HA) the effect was less pronounced, with a tendency toward increased mRNA levels." (PMID 41144538, 2025). "Targeting TERT’s non-canonical functions could achieve anti-cancer effects independently of the telomere lengths of tumor cells." (PMID 40227701, 2025). "However, metastasis in the absence of TERT/ATRX alterations was also evident in three metastatic tumours for two patients (E158, E159)." (PMID 38978571, 2024). "In contrast, the TERT-negative tumor exhibited successful I-131 reuptake with a TDS of −0.060." (PMID 38642578, 2024). "Meaningful nuclear TERT expression was observed in these tumors, concurrent with the overexpression of nuclear survivin, nuclear estrogen, and progesterone receptors as part of the tumor phenotypes (not shown)." (PMID 38698774, 2024). "Moreover, our study found no significant prognostic impact from other tumor biomarkers, such as IDH and TERT promoter mutations." (PMID 38571508, 2024). "Importantly, of the tumor collected at progression in cohort 1, we found 2 patients to have new tumor mutations that were not present at baseline: NRAS and TERT promoter." (PMID 39446377, 2024). "However, the mean TERT expression levels were not significantly different in tumor samples of patients carrying any of the three rs10069690 genotypes (p = 0.102; Kruskal-Wallis test)." (PMID 36768147, 2023). "The highest TERT copy number was 13.40 in tumor tissue and 2.28 in non-tumor tissue." (PMID 37858127, 2023). "The mechanism(s) underlying these effects need to be explored to identify cellular pathways being (de)regulated by telomerase during the oncogenic process to establish how the selective targeting of TERT can rapidly interrupt the expansion of tumour cells, regardless of telomere length and erosion." (PMID 37345011, 2023). "Together, these data suggest that, since the rate of MGMT promoter methylation drops sharply below a TERT promoter VAF of ~ 0.18 (i.e., ~ 35–40% tumor cellularity) for IDHwt GBM, cases with such low VAF may be at increased risk of false-negative MGMT promoter methylation results by pyrosequencing." (PMID 37919784, 2023).
tumor (continued). "Moreover, adoptive transfers of high-avidity TERT-specific TCR-T cells in the context of HLA-A*02:01-restricted targets have been shown potential for controlling tumor growth and prolonging the survival of tumor-bearing mice in AML." (PMID 35356211, 2022). "In addition, further analysis revealed that in metastatic HSCs, the expression of TERT was significantly decreased, while the expression of IL1A was significantly increased, suggesting that cuproptosis might play an essential role in tumor metastasis." (PMID 35875097, 2022). "In conclusion, the mechanisms by which methylation in the TERT promoter region regulates gene expression in different tumor diseases are not entirely the same and may be methylation-dependent or methylation-independent, requiring precise and targeted studies." (PMID 35739589, 2022). "For CHC patients, TERT and ALKBH5 are found to be integrated by HBV fragments in 4 tumors and 2 tumors respectively; interestingly, FN1 is also the only gene with HBV integration event occurred in more than 2 non-tumor samples, which is consistent with the results of ICC samples." (PMID 36123506, 2022). "Interestingly, we also compared their expression levels between tumor and normal tissues and found that the expressional changes were complex, especially significantly upregulated genes (CDKN2A, MYCN, PLK1, and TERT) and some downregulated signatures (AXL, ID1, and TLR3)." (PMID 35754848, 2022). "Importantly, it has been established that the molecular features of gliomas, i.e. IDH-, 1p/19q- and TERT-Status, do not change during tumor recurrence and/or progression." (PMID 35018523, 2022). "In particular, we considered the possibility that epigenetic changes to the TERT locus could in fact act as a cooperative factor in tumorigenesis or tumor cell maintenance rather than as a consequence of TERT promoter mutations." (PMID 34486523, 2021). "Additionally, TERT alterations of de novo HGMs had no predictive effect on tumor recurrence in progression group following postoperative RT (p = 0.074 with log-rank test)." (PMID 34778063, 2021). "More recently, a preclinical study evaluating the co-administration of TERT vaccine with immune checkpoint blockade (anti-CTLA-4) has revealed that a synergistic effect could be achieved, resulting in suppression of tumor growth accompanied by increased survival." (PMID 34440361, 2021). "Tumour TERT RNA abundance was not correlated with tumour TL or TL ratio." (PMID 34824250, 2021). "Also, the two tumours with established TERT promoter mutations and TERT mRNA expression that were negative on ISH using both TERT probes were not the two oldest cases among the mutation-positive tumours (data not shown)." (PMID 34011619, 2021). "TERT reactivated expression was detected in 23/63 (36.5%) mPPGLs, as well as in two clinically aggressive tumor samples and four non-mPPGLs with short/unknown follow-up." (PMID 34638246, 2021). "Tumor purity scores, calculated using the ESTIMATE tool, were associated with FGFR3, but not PIK3CA or TERT mutations, which could be explained by a positive association between the Uro subtype and tumor purity." (PMID 31609466, 2020). "Second, overexpression of TERT in mouse hippocampal NSCs does not lead to tumor formation." (PMID 33330101, 2020). "Thus, on contrary to the effect of HIV-RT, expression by 4T1luc2 cells of RT domain of TERT did not lead to increase of their tumorigenicity, but instead restricted or even prohibited tumor growth." (PMID 32570805, 2020).
tumor (continued). "As c-MYC is known to upregulate TERT expression, TERT interaction with BRG1 may create a positive feedback loop that co-enhances telomerase activity and cell proliferation, both of which are beneficial to tumor development." (PMID 32599885, 2020). "The levels of TERT mRNA did not significantly differ with tumor stage or grading." (PMID 33113831, 2020). "Therefore, endowed with these non-telomeric functions, TERT can participate in all the major characteristics of the cancer phenotype, thereby supporting its role as a potential prognostic tumor marker." (PMID 33113831, 2020). "Thus, we found the main immunogenic region of TERT to be localized in its RT domain, whereas immune response to other TERT regions was either autoimmune in nature or dispensable as not related to the immune clearance of TERT-expressing tumor cells." (PMID 32570805, 2020). "Therefore, the relationship between the mutant TERT promoter and GABPA is more complicated than expected, and GABPA may act as either a tumor-driver or suppressor in context-dependent manners." (PMID 31802036, 2020). "TERT mRNA expression without the concomitance of lymphocytic infiltration, may indicate tumours be followed with caution." (PMID 32659948, 2020). "However, there is only one report describing telomerase activity in FOSCC samples and studies regarding expression of TERT and its correlation with enzymatic activity in these types of cancer are lacking, particularly in tumor-derived living cells." (PMID 32292795, 2020). "These cells named tumor-initiating cells (TICs) or CSCs, have the stem cell-like properties such as the ability of self-renewal, colony formation, and EMT as well as induce resistance to chemotherapy and radiation therapy and telomerase reverse transcriptase (TERT) expression." (PMID 32760219, 2020). "In tumor tissue, the promoter, non-coding exons or introns of five genes were found to be fused to HBV in 2 or more chimeric transcripts, with three different regions of the TERT promoter being fused to HBV in chimeric transcripts from three different patients." (PMID 31429776, 2019). "The tumor harboring this mutation was diagnosed as MTC and had no known hotspot TERT mutations." (PMID 31408918, 2019). "A recent PanCancer study cross 31 tumor types demonstrated that 73% of the analyzed samples expressed TEL, 5% was associated with ALT, while the remaining 22% of tumors neither expressed clear TERT nor harbored ALT-associated alterations." (PMID 31750255, 2019). "TERT mutations were observed in IDH wildtype initial (Chr5: 1254594; Chr5: 1294166) and recurrent tumours (Chr5: 1,254,594); however, none coincided with known somatic mutations in promoter regions at the C228 (Chr5: 1,295,228) and C250 loci (Chr5: 1,295,250; hg19)." (PMID 32082376, 2019). "Both data suggest that, in contrast to the discovery in tumor cell entities and blood cells, TERT:RelA might not establish a reciprocal interplay in the aging CNS." (PMID 30472697, 2018). "In NBLs, the TERT rearrangements were almost mutually exclusive with MYCN and ATRX (associated to another TMM, ALT), stratifying them in two groups of NBLs with very high risk, reinforcing the concept that tumours do not present multiple TMM simultaneously." (PMID 29751586, 2018).
tumor (continued). "While TERC can be found in abundance in tumor and non-tumor cells, the catalytic subunit TERT is expressed in cells with self-renewal activity such as hematopoietic stem and progenitor cells (HSPCs), proliferating lymphocytes and the regenerative basal layer of the epidermis in human skin." (PMID 29143804, 2017). "Indeed, TERT generates immunogenic epitopes for both major histocompatibility complex (MHC) class I and II pathways, able to trigger an adaptive cytotoxic T lymphocytes (CTL) response against tumour cells." (PMID 29152058, 2017). "However, the expression of cytoplasmic TERT and its impact on clinical progression have not been evaluated in the tumor tissues of HCC." (PMID 28460432, 2017). "TERT may, thus, be strictly involved in regulating critical SCC-related pathways, such as Wnt/β-catenin and NF-kB signaling, in a feed-forward loop context that amplifies and sustains autonomous cancer cell proliferation and tumor progression." (PMID 27501725, 2016). "Furthermore, mice transplanted with only TERT-CAR T cells were 100% viable with no tumor formation after 90 days of injection." (PMID 27462436, 2015). "Because TERT gene expression is not always correlated with the enzyme activity, many studies have found that either the telomerase activity or the TERT expression is a marker of tumor aggressiveness and poor prognosis." (PMID 24758186, 2014). "Its gene product, WRAP53 (telomerase Cajal body protein, TCAB1) specifically interacts with TERT (AS on PI3K ablation) and essentially regulates telomerase trafficking, Cajal body formation and telomerase function and is thus of key importance for survival of particularly tumor cells." (PMID 23383294, 2013). "This TERT function is independent of its role at telomeres and could contribute to tumorigenesis by increasing the proportion of CSCs within a tumor." (PMID 23061047, 2012). "In different tumor cell lines, the activity of the survivin gene promoter varies from 0.3 to 16% of the activity of the CMV promoter, while the efficacy of the performance of the TERT promoter may differ by up to 20 fold." (PMID 22649681, 2011). "It should be noted that, due to its extratelomeric functions, TERT represents a promising therapeutic target at all disease stages, as its inhibition restricts the proliferative ability and induces apoptosis regardless of the tumor cell telomere length, while synergizing with standard chemotherapy." (PMID 40227701, 2025). "If we take into account all the tumor samples analyzed in each of the 7 PTCs showing TERT amplification, regardless of the histotype observed in each area of the case under investigation and whether the sample corresponded to a pT, LNM, or DM, then 100% of the cases turned out to be subclonal." (PMID 40272676, 2025). "TERT C228T is a tumor marker that might not be influenced by inflammation." (PMID 35306637, 2022). "Hence, the present results also showed that TERT C228T was a tumor marker that might not be influenced by inflammation." (PMID 35306637, 2022). "Similarly, Wnt ligands released within the tumor microenvironment may drive TERT expression without compensatory upregulation of other telomerase components." (PMID 35159075, 2022). "Therefore, tumours with striking telomere shortening but negative for TERT expression and analysed alterations may be at an early stage of the immortalization process, and these patients could benefit from specific and extended follow‐up strategies." (PMID 35979662, 2022).